DSC3 (desmocollin 3)
Diseases named in the same sentence as DSC3 in open-access papers (continued):
Sharing a sentence is not in itself a finding about the gene and the disease.
chondrosarcoma (1 paper, 2011). A malignant cartilaginous matrix-producing mesenchymal neoplasm arising from the bone and soft tissue. "While epigenetic changes in the expression of maspin, 14-3-3σ, desmocollin 3, and E-cadherin in chondrosarcoma cells and in other cancers are associated with the EMT or MET transitions, the extent to which they are a contributing factor to these process remains to be determined." (PMID 21559267, 2011). "We observed that chondrosarcoma cells acquired the expression of four epithelial markers, E-cadherin,desmocollin 3, maspin, and 14-3-3σ, all of which are governed epigenetically through cytosine methylation." (PMID 21559267, 2011). "In summary we show that chondrosarcoma cells acquire four epithelial-specific markers maspin, 14-3-3σ, desmocollin 3, and E-cadherin, which when taken together, is suggestive of chondrosarcoma cells undergoing to some degree an MET transition." (PMID 21559267, 2011). "To first investigate whether that our chondrosarcoma cells were acquiring more epithelial-like characteristics we queried the expression of four separate epithelial markers: E-cadherin, desmocollin 3, maspin, and 14-3-3σ." (PMID 21559267, 2011).
colitis (1 paper, 2006). Inflammation of the colon. "In tumours on a background of colitis, loss of Dsc2 was observed in eight of 19 specimens examined, and de novo expression of Dsc1 and Dsc3 was detected in 11 of 19 and six of 19 specimens respectively." (PMID 17088906, 2006). "Loss of Dsc2 (8/19) and de novo expression of Dsc1 (11/19) and Dsc3 (6/19) was also found in colorectal adenocarcinomas on a background of colitis." (PMID 17088906, 2006).
colorectal adenocarcinoma (1 paper, 2006). The most common type of colorectal carcinoma. "We have found switching between desmocollins in sporadic colorectal adenocarcinoma with a reduction in Dsc2 protein (in 8/16 samples analysed by immunohistochemistry) being accompanied by de novo expression of Dsc1 (16/16) and Dsc3 (7/16)." (PMID 17088906, 2006).
Erythema (1 paper, 2019). Redness of the skin, caused by hyperemia of the capillaries in the lower layers of the skin. "Unlike the DSG3 and DSC3/DSG3 models, the main features of DSC3 mice consisted of an intense erythema." (PMID 31275323, 2019).
fibrocystic disease (1 paper, 2005). "In addition, we analyzed two benign fibrocystic disease specimens and in both cases we saw no methylation of the CpG island and DSC3 gene expression in one of two specimens analyzed." (PMID 16168112, 2005).
infarction (1 paper, 2024). A localised pathological necrosis of tissue resulting from obstruction of the blood supply usually by a thrombus, an embolus, or vascular torsion. "Functional analysis of SPRR1A, a DSC3 interactor, revealed its unique interaction with miRNA during cardiac fibroblast activation upon post-infarction remodeling." (PMID 39457608, 2024).
lymphadenitis (1 paper, 2019). Acute or chronic inflammation of one or more lymph nodes. "In a supervised comparison between NS cHL fibroblasts and those from lymphadenitis, only one gene turned out to be differentially regulated: DSC3, which was downregulated by 4.7-fold in NS cHL fibroblasts (p < 0.05 and a false discovery rate (FDR) < 0.3)." (PMID 31671543, 2019).
mucinous carcinoma (1 paper, 2005). "The one mucinous carcinoma specimen analyzed showed a loss of DSC3 expression with a concomitant increase in cytosine methylation." (PMID 16168112, 2005). "DSC3 expression is reduced to less than 10% of the expression seen in HMEC in 18 of 24 (75%) of the IDCs, 5 of 7 (71%) ILCs, and in the mucinous carcinoma." (PMID 16168112, 2005).
tumor (28 papers, 2005 to 2025). "DSC3 protein expression was positively associated with tumor-infiltrating immune cells (TIL) (OR 5.663; 95% CI 1.98 to 16.17; p = 0.001)." (PMID 40422563, 2025). "DSC3 expression was associated with tumor-infiltrating lymphocytes in a stage-specific immunogenetic signature." (PMID 40422563, 2025). "De novo expression of Dsc1 and Dsc3 was not entirely dependent on loss of Dsc2 as Dsc1 was expressed in all tumour specimens and Dsc3 was detected in three of eight samples that showed normal levels of Dsc2." (PMID 17088906, 2006). "The relationship between DSC3 and tumor-infiltrating immune cells, treatment outcome, and survival is also not described." (PMID 40422563, 2025). "The findings suggest that immune response to tumor cells is minimal in NMIBC expressing high-DSC3 genes." (PMID 40422563, 2025). "DSC3, another cadherin gene, improves upon both tumor selectivity and safety in HNSC (AUC = 0.91 and FDR p = 0.065; TS safety = 8.96; and HPA safety = 1.68) and encodes the desmocollin-3 protein." (PMID 37835579, 2023). "We found that RBPMS2 and DSC3 are prognostic biomarkers for tumor progression in progressive and de novo MIBC, respectively." (PMID 33731721, 2021). "RBPMC2 and DSC3 were found as independent prognostic biomarkers of tumor progression and CALD1 and LCOR were identified as prognostic biomarkers of CSS between both groups." (PMID 33731721, 2021). "Transcriptional repression of MASPIN, a tumor-suppressor gene involved in angiogenesis, and desmocollin 3 (DSC3), an inhibitor of cell motility, by aberrant DNA methylation has been reported." (PMID 24195060, 2013). "When we further analysed the effect of methylation on clinical outcome by Kaplan–Meier analysis, we found that tumours with methylated DSC3 DNA were significantly correlated to a worse clinical outcome than unmethylated tumours (P=0.002)." (PMID 21364582, 2011). "As before, increases in Dsc1 and Dsc3 mRNA (>2-fold) were detected in a significant number of cases (three of seven and four of seven tumours respectively)." (PMID 17088906, 2006). "From these specimens, total RNA was collected and DSC3 expression was analyzed by quantitative real time RT-PCR with expression levels of the tumor samples being normalized to HMECs." (PMID 16168112, 2005). "As aberrant cytosine methylation of promoter regions is associated with alterations to chromatin structure, we also compared the in vivo nuclease accessibility of the DSC3 promoter region in normal and tumor breast cell lines." (PMID 16168112, 2005). "The proportion of tumor cells expressing DSC3 ranged from 5% to 75%." (PMID 40422563, 2025). "Expression of DSC3 by normal cells also suggests that DSC3 is more likely to be a tumor-associated antigen rather than a neoantigen." (PMID 40422563, 2025). "DSC3 has been shown to serve as a prognostic marker for some cancers, with low expression indicating poor prognosis, suggesting it could be a novel tumor suppressor in some cancers, such as prostate." (PMID 39534596, 2024). "The present result showed that DSC3 gene expression levels were higher in the T2 cell line than A3 and A5 cell lines, indicating that altered expression levels of adhesion molecules depend on the tissue microenvironment of the tumor formed in the animal." (PMID 36293530, 2022). "To define whether desmosomal genes are involved in the antitumor effects of SOX30, we focused on the most differentially expressed desmosomal genes associated with SOX30 and chose the three prominent tumor suppressors DSP, JUP and DSC3." (PMID 29855376, 2018). "Desmocollin 3 has been described as a tumor suppressor of several types of cancer." (PMID 27023475, 2016).
tumor (continued). "Furthermore, other members of the desmosomal cadherin family were expressed at low level in a small number of TCGA tumors, and DSG1, DSC2 and DSC3 were all significantly enriched in the DSG2-high tumor subset." (PMID 27340778, 2016). "We also analysed the DSC3 protein expression in these 99 primary tumours by immunohistochemistry." (PMID 21364582, 2011). "Methylation of DSC3 DNA was detected in 41 out of 99 tumours (41.4%)." (PMID 21364582, 2011). "Similarly, tumours with methylated DSC3 DNA were significantly correlated to a worse clinical outcome in comparison with unmethylated tumours." (PMID 21364582, 2011). "DNA from freshly isolated tumor specimens was analyzed for cytosine methylation by sodium bisulfite sequence analysis while RNA from the same tumors was analyzed by quantitative real-time RT-PCR for DSC3 expression." (PMID 16168112, 2005). "As an active immunotherapy, Mw can activate CD8+ T cells to target DSC3 expressing cancer cells while downregulating tumor induced immunosuppression by decreasing intratumoral FoxP3 and PD-1 expressing immune cells; thus, Mw can be effectively used for management of cancers expressing DSC3." (PMID 39534596, 2024). "Univariate and multivariate regression analysis for tumor progression showed that expression of RBPMS2 and DSC3 were found to be independent prognostic biomarkers in progressive and de novo MIBC groups, respectively." (PMID 33731721, 2021). "Progressive and de novo MIBC groups present different prognostic biomarkers for tumor progression (RBPMS2 in progressive MIBC and DSC3 in de novo MIBC) and for CSS (CALD1 in progressive MIBC and LCOR in de novo MIBC)." (PMID 33731721, 2021). "Genes that were downregulated and hypermethylated in ADCs were squamous markers such as DSC3 and KRT5, as well as transcription factors such as FOXE1 and TP73, whose isoforms have demonstrated both tumor suppressor and oncogenic properties." (PMID 28787442, 2017). "In Cluster 1, we found no genes associated with progressive stages of neoplasia with an FDR < 0.05; however, we observed decreased expression of DSC3 and GPR87 with an FDR < 0.10." (PMID 40844321, 2025). "It is interesting to note that a significant number of mRNAs from the signatures of genes suppressed during EMT, including FOXA1, DSC3, RARRES1, PTEN, and RARRES1, have characteristics of tumor suppressors, including inhibiting hypoxia, tumor cell proliferation, and tumor cell invasion." (PMID 36980175, 2023). "On the other hand, studies have indicated a negative significant difference between ER statuses and DSC3 levels since expression levels were higher in normal tissues than in tumors, indicating a possible tumor suppressor gene function." (PMID 36293530, 2022). "Other signature genes (TP63, CERS3, CSTA, CLCA2, DSC3 and DSG3) upregulated in C1 tumours are also markers of the squamous-like subtype, while further columnar-like marker genes (MUC5B and RGL3) are upregulated in C2 tumours." (PMID 36207323, 2022). "To further investigate whether upregulation of DSP, JUP and DSC3 are necessary for SOX30-medicated tumorigenesis and metastasis in vivo, we utilized a xenograft tumor model using these stable cell lines." (PMID 29855376, 2018). "Q-PCR analysis of an independent cohort revealed DSC3 transcript down-regulation, both in PCa cell lines and tumor tissues but not in their benign counterpart." (PMID 24664224, 2014). "Nonetheless, methylation of the DSC3 promoter correlates with a lack of expression of DSC3 in a significant proportion of the primary tumor specimens examined." (PMID 16168112, 2005). "MCF10A cells, which express DSC3 mRNA, showed protein expression comparable to the HaCaT cells; however, no protein bands were present in any of the tumor cell lines examined." (PMID 16168112, 2005).
tumor (continued). "Tumor samples of Inserm series were predicted in 2 and 4 subtypes molecular classification using a predictor based on nine genes: ADAM19, ETS1, and PDCD1LG2 for C1 and C2; CLDN1, DSC3, and SLC24A3 for C1A and C1B; CHL1, ECM2, and PTPN13 for C2A and C2B subtype prediction." (PMID 32083805, 2020). "Finally, in the two remaining tumor cell lines that express DSC3 we saw little or no methylation of the promoter region." (PMID 16168112, 2005). "However, the downstream signaling pathway of these desmosomal genes in regulating tumor progression is not entirely clear, except for the three canonical tumor suppressor desmoplakin (DSP), junction plakoglobin (JUP) and desmocollin 3 (DSC3)." (PMID 29855376, 2018).
cancer (19 papers, 2006 to 2025). A tumor composed of atypical neoplastic, often pleomorphic cells that invade other tissues. "Increased amounts of message encoding both Dsc1 and Dsc3 were detected in cancer specimens." (PMID 17088906, 2006). "Desmocollin 2 and 3 (DSC2 and DSC3) expressions are well-known prognostic indicators in various cancers, related to adhesive strength, cytoskeletal arrangement, and cell adhesion." (PMID 40872572, 2025). "Moderate/strong cytoplasmic positivity was seen in HNSC, while DSC3 was generally lowly expressed in most other cancers." (PMID 37835579, 2023). "DSC3 gene was chosen from the selected gene set as the most discriminating gen by mRMR algorithm to differentiate among the 7 cancer-related skin states." (PMID 29750795, 2018). "Even so, DSC3 allows separating those skin states that present a greater probability of provoking malignant tumor formations and spreading (PRIMEL, METMEL and MCC) from those less aggressive or simply healthy skin states (BCC, SCC, NSK and NEV)." (PMID 29750795, 2018). "Pyrosequencing confirmed the increased DSC3 promoter methylation in cancer cell lines and restoration of transcript expression upon 5-Aza treatment further corroborated this epigenetic silencing mechanism." (PMID 24664224, 2014). "Supporting the trend observed with the publically available data, pyrosequencing analysis revealed frequent hypermethylation of DSC3 promoter in cancer cell lines (3/3) compared with benign cell lines (0/2) (10% methylation as a cutoff)." (PMID 24664224, 2014). "Protein expression was analysed by western blotting showing decreased expression of DSC3 in cancer cell lines." (PMID 21364582, 2011). "Two members of the cadherin family of cell adhesion molecules E-cadherin and desmocollin 3, have been shown to be downregulated in several types of cancers through DNA methylation." (PMID 21559267, 2011). "There is evidence that Mw targets desmocollin-3 (DSC3) expressing cancer cells." (PMID 39534596, 2024). "A study on CRC cells shows Dsc2 is switched to Dsc1 and Dsc3 during cancer development." (PMID 35194111, 2022). "Our analysis also showed consistent downregulation of DSC3 mRNA in cancer cell lines." (PMID 24664224, 2014). "We found that the cancer subtype markers (GRP, CHGB, NEUROD1, and CHGA for NET; KRT5, DSC3, KRT6B, TP63, and KRT6A for SCC; and NKX2-1, KRT7, NAPSA, and MUC1 for ADC) were specifically expressed in the corresponding cancer subtypes." (PMID 35962452, 2022). "In DSC3 negative cancers, there are effective therapies described to convert DSC3 negative tumors to DSC3 positive status, even at a subtherapeutic dose." (PMID 39534596, 2024). "Additionally, its expression adds complementary information to what it is already provided by DSC3 and SCGB2A1, providing a better discernment among the 7 cancer-related skin states." (PMID 29750795, 2018).
adenocarcinoma (4 papers, 2006 to 2017). A common cancer characterized by the presence of malignant glandular cells. "Three genes (DSC3, KRT6A and DMRT2) were predicted as targets of miR-375, the miRNA upregulated in adenocarcinoma, and these genes were consistently down-regulated in this histological subtype." (PMID 24625834, 2014).
DSC3 also shares sentences with these, for which no sentence is quoted: cervical cancer (2 papers); metastatic melanoma (2); oral cancer (2); ovarian carcinoma (2); Arrhythmia (1); Arthritis (1); bullous pemphigoid (1); COVID-19 (1); cutaneous melanoma (1); esophageal squamous cell carcinoma (1); head and neck cancer (1); hypotrichosis (1); infection (1); influenza (1); invasive ductal carcinomas (1); invasive lobular breast carcinoma (1); meningioma (1); metastatic cancer (1); nasopharyngeal carcinoma (1); oral squamous cell carcinoma (1); Palmoplantar keratoderma (1); pediatric acute lymphoblastic leukemia (1); psoriasis (1); schizophrenia (1); squamous non-small-cell lung cancer (1); Ventricular arrhythmia (1).